BAX (BCL2 associated X, apoptosis regulator)
Diseases named in the same sentence as BAX in open-access papers (continued):
Sharing a sentence is not in itself a finding about the gene and the disease.
tumor (continued). "Protein levels of MS4A10, MS4A8, MS4A7, PCNA, BAX, Bcl-2, Caspase-3, and cleaved Caspase-3 were measured in tumor tissues." (PMID 36438804, 2022). "Regions that encode gene products (proteins) involved in tumor suppression (e.g., TGFBR2), cellular growth, DNA repair (e.g., MSH3, MSH6), and apoptosis (e.g., BAX) contain repeat sequences, and genetic changes are likely to occur in these regions." (PMID 34185173, 2021). "We therefore investigated the ability of MCL-1 deletion to suppress MMTV-PyMT tumour growth when the downstream apoptotic effectors BAX/BAK were reduced." (PMID 33785871, 2021). "Analysis of apoptosis-related genes, including BAX, BCL2, and CASP3, and also BAX/BCL2 ratio indicated CAP induces apoptotic pathway selectivity in tumor cells." (PMID 34825002, 2021). "Over-expression of BCL-XL or knockdown of [BAX + BAK] significantly reduced tumor cell killing, implying that mitochondrial dysfunction played an important role in the killing process." (PMID 34490108, 2021). "These include the densities of tumor cells and CSCs, and the concentrations of intracellular signaling molecules (NFκB, Bcl-2, BAX)." (PMID 34669701, 2021). "In the case of tumour cells, it has been shown that there is an increase in the threshold of apoptosis activation by downregulation of BAX and SMAC16,35,39." (PMID 33558564, 2021). "In particular, we minimize tumour volume and maximize the apoptotic potential by minimizing the Bcl-2 concentration and maximizing the BAX level while minimizing total injection amount of both IFN-β and JAK2 inhibitors (DDP)." (PMID 34631119, 2021). "In our results indicated the combination group presented significantly higher expression of granzyme-B and apoptotic proteins (BAX and cleaved-caspase-3) in CT-26 or B16-F10 tumor tissues compared to hIL15-ABD or anti-PD-L1 therapy." (PMID 33918641, 2021). "RT-qPCR of mRNA isolated from six independent tumour lysates showed significantly higher expression of BAX too." (PMID 32973362, 2021). "The results show that the levels of BAX and cleaved caspase‐3 have increased and that of Bcl‐2 has decreased in tumours of the gracillin‐treated mice." (PMID 33259114, 2021). "Green tea and Qu decreased growth of tumor in HL-60 xenografts escorted by reduced antiapoptotic protein expression and enhanced BAX expression, a proapoptotic protein." (PMID 33804548, 2021). "Western blot for BAX from 6 independent tumour lysates revealed approximately twofold more BAX protein in LV-miniMg-∆MEF3/NF1-HSV tumours compared to LV-∆miniMg-HSV controls." (PMID 32973362, 2021). "The regulators of apoptosis also include the anti-apoptotic protein Bcl-2 (B cell lymphoma/leukemia-2) and the pro-apoptotic protein BAX, which affect the function of cell caspases; in many neoplasms, an increase in Bcl-2 expression is often observed." (PMID 34830452, 2021). "Recently, the restoration of the BAX axis in TNBC has been demonstrated to hinder tumor progression." (PMID 34833068, 2021). "Our results showed the combination therapy increased BAX/BCL2 ratio in both tumor and normal cell lines than CAP or CUR treatments." (PMID 34825002, 2021).
tumor (continued). "On the other hand, a combination (TZB+ATV) therapy can increase the anti-tumor efficacy by decreasing the overall expression levels of IL-6, NFκB (green dashed), and Bcl-2 (red solid), and by increasing the overall BAX levels (blue circle)." (PMID 34669701, 2021). "Using protein lysates obtained from the xenografted tumor tissues, treatment with flubendazole caused a decrease in the levels of p-STAT3 and induced the expression of apoptosis protein of BAX; meanwhile, the BCL2 level was reduced." (PMID 34513827, 2021). "In a subgroup of patients, BAX shifts to the cytosol accompanied by fundamental molecular changes in the tumor cells." (PMID 32486514, 2020). "Knock down of MCL-1 or BCL-XL enhanced tumor cell death whereas over-expression of BCL-XL was protective as was knock down of BAX, BAK and BAD." (PMID 32047722, 2020). "Resulting tumors showed distinct patterns of molecular changes in hallmark oncogenic signaling validating the functional differences in BAX regulation and the tumor classification." (PMID 32486514, 2020). "To clarify the mechanism of Septin4 in promoting the apoptosis of tumor cells, we found that Septin4 can interact with BAX and enhance this interaction following stimulation with DOX." (PMID 32398959, 2020). "Consistently, GSEA analyses demonstrated that the BAX-protected profile was highly enriched in a prognostic subtype of 139 patients with aggressive tumor biology and poor differentiation." (PMID 32486514, 2020). "Apoptosis of tumor cells under the influence of ABT-737 can be induced if the cell contains a sufficient amount of BAX and Bak." (PMID 33218059, 2020). "We observed a significant increase in the mRNA fold change of NEU2 along with a few pro-apoptotic genes such as CASPASE 3/8, and BAX in Neu2-overexpressed tumor tissue samples as compared to vehicle control." (PMID 32575925, 2020). "The importance of limiting the mitochondrial BAX pool is particularly apparent for a subgroup of tumors with high mitochondrial BAX levels in corresponding non-tumor cells." (PMID 32486514, 2020). "Despite common cellular control of BAX and BAK particular low mitochondrial BAX levels are apparent in tumor cells." (PMID 32486514, 2020). "This subgroup is selected for minimizing the mitochondrial BAX pool manifested in a predominant cytosolic BAX localization in tumor cells to protect itself specifically from BAX activation." (PMID 32486514, 2020). "The BAX localization shows a slight inverse correlation to total protein levels in the tumor consistent with human AML." (PMID 32486514, 2020). "In CLL, this was attributed to a tumor-specific increase in apoptosis, associated with a decreased BCL2/BAX ratio." (PMID 32517377, 2020). "These tumor tissues showed downregulation of several stem cell markers, Shh and mTOR proteins as well as upregulation of pro-apoptotic (BAX/CAS3/CAS8) genes." (PMID 32575925, 2020). "PNP3 (5 and 10 mg/kg) was evaluated for the antitumor potential against SEC grown in female mice by measuring the tumor mass as well as the expression and immunohistochemical staining for the apoptosis markers; caspase 3 and BAX." (PMID 32679837, 2020). "Heavy ion beams can exert anti-tumor effects by upregulating the pro-apoptotic gene BAX and inhibiting the anti-apoptotic gene BCL2, which inhibits MMP2 and MMP9 expression and angiogenesis in tumors." (PMID 33330321, 2020). "Further, immunoblot analysis revealed a significant increase in p21 and BAX proteins in the tumor tissue lysates of animals fed PEITC diet." (PMID 31307507, 2019).
tumor (continued). "IHC on xenograft tumors with antibodies to apoptosis related genes including BCL-2 and BAX also confirmed Cisplatin with ASC-J9® treatment had the best suppressive effects on xenografted miBCa tumor growth via increased miBCa cell apoptosis." (PMID 31234917, 2019). "In this context, massive BSB-induced BID translocation would disengage the activator BIM from its binding partners or directly activate the effectors BAK/BAX, successfully overwhelming tumor anti-apoptotic reserves." (PMID 31767857, 2019). "The destruction of the balance between Bcl-2 and BAX can result in tumor cells that are resistant to chemotherapy drugs." (PMID 30842340, 2019). "To validate these in vitro result, we also measured expression level of BCL-2 and BAX protein expression in xenograft tumor." (PMID 31450709, 2019). "One the other hand, expression of pro-apoptotic proteins BAX was significantly increased in the tumor of ECPU-0001 treated nude mice." (PMID 31450709, 2019). "RT-qPCR analysis revealed that, compared with the sh-NC group, the mRNA expression level of LC3B and BAX mRNA was increased in the sh-CASC9 tumor tissues, whereas the mRNA expression level of P62 and BCL-2 was decreased (P < 0.05)." (PMID 30674868, 2019). "We also determined the apoptosis by ELISA assay and RT-PCR method of BAX, Bcl-2, and Caspase 3 levels in tumor tissues of H22 tumor-bearing mice and SMMC-7721 cells." (PMID 29636773, 2018). "We used the ELISA assay to investigate the effects of TF on the levels of BAX and Bcl-2 in tumor tissues of H22 tumor-bearing mice." (PMID 29636773, 2018). "Here, the authors perform a genome-wide CRISPR/Cas9 screen and identify VDAC2 as a promoter of BAX-mediated apoptosis that is important for an efficient chemotherapeutic response and to suppress tumor formation." (PMID 30478310, 2018). "We found that NEAT1 inhibition plus DDP in vivo inhibited the BCL-2/caspase-3 levels and increased the BAX expression for tumor apoptosis, and also repressed the cyclin D1/CDK4 expression for cell cycle arrest." (PMID 29654165, 2018). "The BCL2/BAX ratio in each renal biopsy analysed was higher in tumour tissue with respect to control tissue due to reduced BAX level." (PMID 29251173, 2018). "As a consequence of BCL2 down-regulation and a rise in BAX level, we detected a remarkable increase in apoptosis levels in tumor cells, whereas PBMCs proved to be unaffected." (PMID 30120339, 2018). "The possibility that miR-34a favors survival of HTLV-1-infected cells by modulating expression of BAX, a known tumor suppressor, merits further investigation." (PMID 29780367, 2018). "Targeted deletion mouse studies can avoid these autoimmune complications and in this setting loss of BAX/BAK in the brain and testicles results in tumours." (PMID 29769323, 2018). "Meanwhile, the expression of Bcl-2 was decreased but the expression of the BAX and Caspase-3 was increased in tumor tissue." (PMID 28514759, 2017). "From the tenth day, BAX depletion markedly enhanced tumor growth when compared with the siNC control group." (PMID 28556798, 2017). "S63845 binds with high affinity to the BH3‐binding groove of MCL1, and selectively induced apoptosis of MCL1‐dependent tumour cells in a BAK/BAX‐dependent manner with ~ 1000‐fold greater potency than A‐1210477." (PMID 28548464, 2017). "The protein expression level of Bcl-2, BAX and Caspase-3 in tumor tissue was analyzed by Western Blot." (PMID 28514759, 2017). "The expression of genes involved in the apoptosis process (BCL2 and BAX) by HepG2 and HL-60 tumor cells treated with CR-LAAO was evaluated by RT-qPCR." (PMID 28205610, 2017). "Since PUMA-mediated cell death seemed to be one of important pathway of IPP-14-induced tumor suppression, we next checked the effect of IPP-14 in PUMA and BAX deficient cell lines." (PMID 28423593, 2017).
tumor (continued). "Compared with normal saline and LNPS@Scrambled Bcl-2 treated tumor-bearing mice, the expression of Bcl-2 significantly reduced, and the expression of BAX and Caspase-3 obviously increased in tumor tissue after tumor-bearing mice were treated with LNPS@siBcl-2." (PMID 28514759, 2017). "The results demonstrated that inhibition of tumor growth was related with the decrease of Bcl-2 protein expression and the increase of the BAX and Caspase-3 protein expression." (PMID 28514759, 2017). "Consistently, immunoblot analysis of these tumour tissues showed a marked increase in the level of apoptotic BAX protein." (PMID 27545325, 2016). "We subsequently measured the expression levels of BAX, Bcl-2, and survivin in all tumor tissues using Western blot." (PMID 27248325, 2016). "The observations from this study, that up-regulation of miR-128 inhibited HNSCC growth through directly mediating its targets Paip2, BAG-2, H3F3B, BMI-1, and BAX in proliferation and apoptotic pathways, support that miR-128 functions as a tumor suppressor." (PMID 25764126, 2015). "BCL2 expression increased over BAX expression with increasing malignancy of the tumor from TC to SCLC." (PMID 26008974, 2015). "The upregulation of BAX proteins increases chemosensitivity of tumor cells to various anticancer drugs." (PMID 24637737, 2014). "This suggests that the in vivo response of the bulk tumor is likely dictated by the drug-induced decrease in Ki67-positive proliferative cells which was similar in BAX +/− and BAX −/− HCT116 tumors." (PMID 24185264, 2013). "This is the first study examining the potential clinical utility of BAX as a prognostic tumor biomarker in NPC." (PMID 23777485, 2013). "Fourteen days after tumor cell implantation, AuNP-αRNA I-5’BAX-null mRNA, AuNP-αRNA I-5’BAX mRNA, or a mixture of lipofectamine and BAX mRNA was subcutaneously injected into the tumors every two days for 21 days." (PMID 24073264, 2013). "The use of AuNP-DNA conjugates to deliver BAX mRNA to xenograft tumors in mice allowed for the synthesis of biologically functional BAX protein, which inhibited tumor growth by inducing apoptosis." (PMID 24073264, 2013). "The delivered mRNA directed the efficient production of biologically functional BAX protein, a pro-apoptotic factor, consequently inhibiting tumor growth." (PMID 24073264, 2013). "The delivery of AuNP-αRNA I-BAX mRNA conjugates into tumor tissues was confirmed by analyzing tumor sections prepared from mice injected with AuNP-αRNA I-Cy3-5'BAX mRNA." (PMID 24073264, 2013). "Consistent with in vitro cytotoxicity results, the volume (mm3) of xenografted tumors injected with the AuNP-αRNA I-Cy3-5′BAX mRNA conjugate was decreased significantly to 40% of the tumor volume in controls treated with AuNP-αRNA I-Cy3-5′BAX-null mRNA." (PMID 24073264, 2013). "Immunoblot analysis of tumor samples demonstrated that the isogenic status of the cell line pair was conserved in vivo with only the HCT116 BAX+/− line expressing BAX protein." (PMID 24185264, 2013). "It was not possible to determine if necrotic cell death was contributing to the overall response of HCT116 BAX−/− tumor xenografts." (PMID 24185264, 2013).
tumor (continued). "In line with an essential function in tumor cell killing, the median survival of BAX positive patients after pancreatic resection is 19 months versus 11 months of BAX negative patients." (PMID 18652674, 2008). "Recent reports by our group and others have suggested the proapoptotic BAX protein to act as a tumour suppressor in human malignancies playing a key role in mediating the apoptotic programme in response to genotoxic stress." (PMID 17426704, 2007). "Any immunoreactivity for BAX was quantitatively detected in 181 (96.3%) tumour specimens: in 15 (8%) between 1 and 60% of cells, in 33 (17.6%) between 61 and 80%, in 39 (20.7%) between 81 and 99%, and in 94 (50%) in all positive stained cells." (PMID 17426704, 2007). "BCL2 has an inhibitory effect on programmed cell death (anti-apoptotic) while BAX is a tumor suppressor that promotes apoptosis." (PMID 17868464, 2007). "There is increasing evidence from other tumour sites showing the role of BAX as a prognostic marker." (PMID 12592374, 2003). "On the other hand, BAX expression was associated with expression of CD40 and CD40L, suggesting that all three are linked in their behaviours in this tumour type." (PMID 12592374, 2003). "Endpoints encompassed body weight, thigh tumor volume, hematological profiling, histology, immunohistochemistry identification of cleaved caspase 3, and real-time PCR quantification of BAX, BCL-2, and caspase 3 mRNA, utilizing the BAX/BCL-2 ratio as an indicator of apoptotic equilibrium." (PMID 41749157, 2026). "In addition, MAL reduces mitochondrial membrane potential and promotes mitochondrial-mediated apoptosis through the BAX/Bcl-2/caspase-3 axis, further amplifying endogenous apoptosis in tumor cells." (PMID 41669875, 2026). "This suggests that BAX may undergo functional reprogramming under the influence of ammonia metabolic dysregulation and the immunosuppressive tumor microenvironment." (PMID 40382614, 2025). "In addition, Rh inhibits tumor growth by activating apoptosis-related proteins, including caspase-3, BCL-2, and BAX, and by suppressing tumor angiogenesis." (PMID 41471822, 2025). "Cell communication analysis revealed an enhanced ligand-receptor interaction network between BAX + tumor cells and immunosuppressive components such as macrophages, monocytes and Tregs, especially involving immune regulatory pathways such as TGF-β and PD-1/PD-L1." (PMID 40382614, 2025). "This indicates that the abnormal expression of BAX may be an important tumor marker, and its role in cell apoptosis cannot be ignored." (PMID 41411247, 2025).